PARP1 (poly(ADP-ribose) polymerase 1)
Diseases named in the same sentence as PARP1 in open-access papers (continued):
Sharing a sentence is not in itself a finding about the gene and the disease.
pancreatic ductal adenocarcinoma (5 papers, 2015 to 2022). An infiltrating adenocarcinoma that arises from the epithelial cells of the pancreas. "The synthetic lethality achieved with PARP1 inhibitors was also observed in pancreatic ductal adenocarcinoma cells with ATM mutation." (PMID 31192117, 2019). "[18F]olaparib was demonstrated to have good selectivity towards PARP1, 2 and 3 in pancreatic ductal adenocarcinoma (PDAC) preclinical models, making [18F]olaparib a good candidate as an imaging tool to study the effects of PARP inhibitor on PARP isoform expression." (PMID 36210377, 2022). "Reducing NAD+ pools by inhibiting NAMPT primed pancreatic ductal adenocarcinoma (PDA) cells for poly(ADP ribose) polymerase (PARP1)-dependent cell death induced by the targeted cancer therapeutic, β-lapachone (β-lap, ARQ761), independent of poly(ADP ribose) (PAR) accumulation." (PMID 25590809, 2015).
prostate tumors (5 papers, 2014 to 2024). "We employed 14 patient-derived tumor graft models pancreatic, lung, and prostate tumor graft models harboring HR mutations (BRCA1/2, CHK1/2, ATM/ATR, PALB2, PARP1/2, RAD51, FANCA/B) to compare LP-184’s potency with PARPi olaparib." (PMID 38630886, 2024). "Several PARP1/2/3 inhibitors (PARPi) have had success in treating ovarian, breast and prostate tumors harboring defects in the homologous recombination (HR) DNA repair pathway, especially BRCA1/2 mutated tumors." (PMID 33005627, 2020). "Notably, SLs induced apoptosis even at lower concentrations in the primary prostate tumor cells, which was confirmed by PARP1 cleavage." (PMID 24742967, 2014).
renal carcinoma (5 papers, 2017 to 2023). A carcinoma arising from the epithelium of the renal parenchyma or the renal pelvis. "Reduction of pADPr by PARP-1 inhibition or PARG overexpression disrupts renal carcinoma cell malignancy." (PMID 34638458, 2021).
stomach cancer (5 papers, 2019 to 2023). "Furthermore, increasing PARP1 levels positively correlate with advanced gastric tumour stage, metastases and poorer survival rates, supporting a role for PARP1 in disease progression." (PMID 34440228, 2021).
systemic lupus erythematosus (5 papers, 2016 to 2025). An autoimmune multi-organ disease typically associated with vasculopathy and autoantibody production. "Using lupus and anti-glomerular basement membrane models of nephritis to determine the effect of PARP1 on renal inflammation, researchers found that the activation of PARP1 and subsequent necrotic cell death is involved in the pathogenesis of male glomerulonephritis." (PMID 35806303, 2022). "Additionally, miR-199a was shown to target PARP-1 and activate the ERK1/2 pathway to promote IL-10 production, suggesting that miR-199a may be a potential therapeutic target of systemic lupus erythematosus." (PMID 33276722, 2020).
uveal melanoma (5 papers, 2020 to 2024). A melanoma derived from melanocytes of the uveal tract. "Going further, the subcellular distribution of DTYMK and PARP1 in uveal melanoma cells was determined through immunocytochemical analyses." (PMID 39195238, 2024). "Since we observed the overexpression of DTYMK and PARP1 in tumors derived from patients with uveal melanoma, we decided to test the influence of inhibitors of these enzymes in the in vitro model." (PMID 39195238, 2024). "In another study utilizing uveal melanoma cell lines, it was reported that inhibition of PARP1 led to retardation or almost complete inhibition of tumor development." (PMID 33572647, 2021). "There are only a few reports in the literature published so far on the role of PARP-1 in uveal melanoma." (PMID 33572586, 2021). "The aim of the study was to evaluate the expression of PARP-1, the best-known member of the family of poly(ADP-ribose) polymerases, in uveal melanoma and its associations with clinicopathological parameters, overall survival, and disease-free survival." (PMID 33572586, 2021). "Murine models have supported a pro-metastatic role for PARP-1, and PARP inhibition is showing early promise in combination with radiotherapy in murine models of uveal melanoma 51,52." (PMID 33214570, 2020). "Taken together, these results indicate the independent role of DTYMK and PARP1 in the pathobiology of uveal melanoma, regardless of BAP1 status." (PMID 39195238, 2024). "Our hypothesis of the double hit into tumoral DNA metabolism as a possible therapeutic option in uveal melanoma was confirmed since combined targeting of DTYMK and PARP1 affected all tested cytophysiological parameters with the highest efficiency." (PMID 39195238, 2024).
acute pancreatitis (4 papers, 2016 to 2023). An acute inflammatory process that leads to necrosis of the pancreatic parenchyma. "As a co-activator of inflammatory transcription factors, PARP1 is a central mediator of the inflammatory response and it has also been implicated in acute pancreatitis." (PMID 33808340, 2021). "A previous study in a secretagogue-induced murine model of acute pancreatitis demonstrated that PARP-1 antagonism (or deficiency) could reduce damage to the pancreas and the lungs." (PMID 27465581, 2016). "Wild-type (WT) and PARP1 knockout (KO) mice were treated with cerulein to induce acute pancreatitis according to the reference given in the Materials and Methods section." (PMID 33808340, 2021). "Supporting our results from PBMCs, olaparib induced a significant decrease in PARP1 activity and recovery of NAD+ levels, and it increased cell viability in an acute pancreatitis model and human monocytic lineage cells subjected to oxidative stress." (PMID 35740913, 2022).
acute respiratory distress syndrome (4 papers, 2021 to 2026). Progressive and life-threatening pulmonary distress in the absence of an underlying pulmonary condition, usually following major trauma or surgery. "On the other hand, treatment with Na2S suppresses ALI caused by burns and smoke by attenuating iNOS expression, peroxynitrite formation, acute respiratory distress syndrome, nitro yield (lysine measurement), protein (oxidized protein carbonyl formation) and PARP-1 activity in vivo." (PMID 34062820, 2021). "Hereon, we intend to explore the impact of PARP-1 on the imbalance of Th17/Treg and the potential mechanism in premature rats with acute respiratory distress syndrome (ARDS)." (PMID 35190759, 2022). "Olaparib, the first clinically approved poly (ADP-ribose) polymerase (PARP) inhibitor, may be repurposed for non-oncological conditions such as acute respiratory distress syndrome (ARDS), where PARP-1 inhibition has shown benefits in preclinical models." (PMID 41840597, 2026).
Anxiety (4 papers, 2015 to 2024). Intense feelings of nervousness, tension, or panic often arise in response to interpersonal stresses. "Consistently, the elevated plus maze test also showed that PARP-1 KO mice exhibited high anxiety, i.e., decrease in open arm duration (Fig. 7b1) and open arm entries (Fig. 7b2)." (PMID 31819047, 2019). "However, no significant change in the total moving distance was detected (Fig. 7a2), suggesting the higher anxiety of PARP-1 KO mice without any changes in locomotor activity." (PMID 31819047, 2019).
brain cancer (4 papers, 2014 to 2024). A primary or metastatic malignant neoplasm affecting the brain. "The PARP1 variant Thr124Ala was inherited from the father (diagnosed with basal cell cancer at 78, and whose mother had brain cancer at 74)." (PMID 30680959, 2019). "In the current meta-analysis, the PARP1 Val762Ala polymorphism seemed to exert opposite effects on the risks of gastric and brain cancer." (PMID 24489833, 2014). "The protective effect of PARP1 Val762Ala polymorphism on brain cancer risk in Caucasian may be associated relative higher Val (T) allele frequency in this ethnic group." (PMID 24489833, 2014). "The expression of PARP1 mRNA and protein has been shown to be upregulated in several malignancies, including breast, ovarian, skin, colorectal, lung, and brain cancers." (PMID 39598347, 2024). "We propose PDE5 as a highly statistically significant prognostic marker of increased OS in GBM patients and identify PKG, ROCK and PARP1 as potential therapeutic targets for this subset of brain cancers." (PMID 28099939, 2017).
Cachexia (4 papers, 2016 to 2024). Severe weight loss, wasting of muscle, loss of appetite, and general debility related to a chronic disease. "Compounds that inhibit PARP1/2-mediated PARylation activity have been shown to ameliorate muscle performance/function in muscle-related diseases such as sarcopenia, Duchene muscle dystrophy, and cachexia." (PMID 38321934, 2024). "PARP activation occurs in the muscles of mice that develop lung cancer, and deletion of either PARP1 or PARP2 reduces body weight loss, decreases the expression of genes involved in muscle proteolysis, and promotes the expression of anabolic markers in lung cancer‐induced cachexia." (PMID 32730698, 2020). "Treatment with the PARP-1/2 inhibitor rucaparib elicited a significant improvement in body weight gain, tumor size and weight, and locomotor movements compared to non-treated cachexia mice." (PMID 35740560, 2022).
Cockayne syndrome (4 papers, 2020 to 2024). A multisystem condition characterized by short stature, a characteristic facial appearance, premature aging, photosensitivity, progressive neurological dysfunction, and intellectual deficit. "In a mouse model of Cockayne syndrome, another premature aging syndrome, treatment with PARP-1 inhibitors promoted lifespan and decreased aging associated phenotypes." (PMID 39353941, 2024). "Interestingly, the lifespan of mice with Cockayne syndrome was prolonged and the severity of symptoms associated with PARP1 overactivation was reduced following treatment with PARP1 inhibitors or NAD+ supplementation." (PMID 38921477, 2024). "A correlation was observed between PARP1 activation, reduced NAD+ levels, and SIRT1 activity inhibition in patients with pigmented keratoses, progeria-like aging, ataxia telangiectasia, and Cockayne syndrome." (PMID 38921477, 2024). "The strong correlation among PARP1 overactivation, limiting NAD+ pools and inhibition of SIRT1 activity is observed in a broad spectrum of human diseases, including xeroderma pigmentosum group A, progeroid diseases, ataxia telangiectasia and Cockayne syndrome." (PMID 37165408, 2023). "Brenna Osborne, University of Copenhagen, Denmark further illustrated that depletion of CD38 appears to exacerbate some of the aging phenotypes in the mouse model of Cockayne syndrome, where another major NAD+-utilizing enzyme poly(ADP) ribose polymerase 1 (PARP1), is hyperactivated." (PMID 33378272, 2020).
cutaneous melanoma (4 papers, 2019 to 2021). A primary melanoma arising from atypical melanocytes in the skin. "The expression of PARP1 was also assessed by immunohistochemistry in formalin-fixed paraffin-embedded tissues of 128 primary cutaneous melanoma patients and correlated with follow-up and clinicopathologic features." (PMID 33572647, 2021). "PARP1 overexpression has been reported to be a potential marker of aggressive clinical behavior in cutaneous malignant melanoma." (PMID 32380691, 2020). "In summary, our studies show that a 2HF–PLO gel is active when applied topically to cutaneous melanoma, that the mechanism of action appears to be through Rlip protein depletion, and that it may enhance the anticancer effects of sunitinib and PARP1 inhibitor." (PMID 31615091, 2019). "Moreover, proteomic analysis of samples derived from patients with stage III skin melanoma (according to the 7th edition of AJCC staging) revealed that elevated PARP1 expression might be one of the markers discriminating patients with better prognosis from those with the worse one." (PMID 33572647, 2021). "Due to the significant correlation between high PARP1 expression and enhanced mitotic activity, potential inhibition of PAPR1 in cutaneous melanoma patients could be beneficial." (PMID 33572647, 2021).
diabetic retinopathy (4 papers, 2020 to 2024). "PARP-1 inhibitors help to restore angiostatin levels, thereby counteracting the abnormal pro-angiogenic state seen in diabetic retinopathy." (PMID 39458649, 2024). "In the future perspectives of diabetic retinopathy (DR) drug research, more attention should be given to the efficient combination of PARP-1 inhibitors with neuroprotective chemicals, such as neuropeptides." (PMID 39458649, 2024). "PARP-1 activation is present in neuropathy and vascular alterations of diabetic retinopathy (DR)." (PMID 39458649, 2024). "PARP1 is shown to activate JNK and DNA binding of AP-1 in fibroblasts and enhance NF-κB/AP-1 binding to MMP9 promoter sequence in diabetic retinopathy, though its role in transcriptional activation of the profibrotic program in Mφ, if any, is not known." (PMID 33172999, 2020). "PARP1 was shown to promote nuclear translocation of RelA (p65) in T. cruzi-infected cardiomyocytes and to enhance NF-κB/AP-1 binding to the MMP9 promoter sequence in diabetic retinopathy and JNK-dependent activation of AP-1 in murine fibroblasts." (PMID 33172999, 2020).
diffuse large B-cell lymphoma (4 papers, 2019 to 2023). "Recent study have demonstrated that inhibition of JNK and PARP1 can reverse miRNA-363-3p-associated doxorubicin resistance in diffuse large B-cell lymphoma." (PMID 36765039, 2023). "In diffuse large B-cell lymphoma (DLBCL) cells, the expression of key MMEJ proteins, including Lig I, Lig III, PARP1, CtIP, and MRE11 elevates, while the level of C-NHEJ factors decreases." (PMID 34732266, 2021).
endometrial adenocarcinoma (4 papers, 2013 to 2024). "DNA from forty normal endometrium (NE) and fifty endometrial adenocarcinoma (EAC) tissues were analyzed by bisulfite sequencing using primers focusing on the core promoter region of PARP1." (PMID 23762867, 2013).
leiomyosarcoma (4 papers, 2016 to 2019). An uncommon, aggressive malignant smooth muscle neoplasm, usually occurring in post-menopausal women. "In addition, when further analysis was performed according to the histologic subtypes of STSs, PARP1 expression was significantly associated with shorter survival of leiomyosarcoma, myxofibrosarcoma, and adult fibrosarcoma." (PMID 27643881, 2016). "In leiomyosarcomas, CINSARC was associated with the PARP1‐based classification and with MFS, whereas strikingly PARP1‐based classification had no prognostic value." (PMID 31131495, 2019). "As expected, the rucaparib inhibited basal PARP-1 activity (reducing the amount of PARylated proteins) in all cell lines, and we observed an effect of trabectedin and combination of drugs only in leiomyosarcoma cells (IB136)." (PMID 28399901, 2017). "A, western blot analysis of PARylation and PARP1 expression in MES-SA and MES-SA-DX5 leiomyosarcoma cells; B, FISH analysis of PARP1 gene (red) and centromere of chromosome 1 (green) in MESSA and MESSA-DX5." (PMID 28454547, 2017). "Of note is that the doxorubicin-resistant leiomyosarcoma cell line MES-SA-DX5 also displayed cross-resistance to trabectedin, but addition of PARP1 inhibitors restored sensitivity to a clinically achievable trabectedin concentration." (PMID 28454547, 2017).
meningioma (4 papers, 2013 to 2019). A generally slow growing tumor attached to the dura mater. "We also detected amplification of both enabled homolog (ENAH) and poly [ADP-ribose] polymerase 1 (PARP1) in CH157-MN, although these genes have not previously been implicated in meningiomas tumorigenesis." (PMID 28552950, 2017).
Myocardial fibrosis (4 papers, 2018 to 2025). "Furthermore, PARP1 knockdown significantly attenuated the MI-induced apoptosis with consistent myocardial fibrosis and related gene expression." (PMID 30323296, 2018).
pancreatic adenocarcinoma (4 papers, 2015 to 2021). "We evaluated the expression of PARP-1 protein in pancreatic adenocarcinoma and normal pancreas tissues by immunohistochemistry." (PMID 32850156, 2020). "Protein PARP-1 in the nucleus was found in all samples (normal pancreas and pancreatic adenocarcinoma tissues)." (PMID 32850156, 2020).
progeria (4 papers, 2015 to 2025). "A plausible mechanism for defective mitophagy in progeroid syndromes, CS, WS, XP and AT, appears to lie in defective DNA damage repair associated with persistent PARP1 activation depleting NAD+ cell reservoirs." (PMID 38481648, 2023). "It has been demonstrated that PARP1 decreases with increasing level of progerin, a common event in cultured progeria cells, associated with increasing passage number." (PMID 26359359, 2015). "Previously, our group demonstrated a critical role of PARP1 in mediating VSMC loss in progeria." (PMID 39422121, 2025).
renal fibrosis (4 papers, 2017 to 2025). A final common manifestation of a wide variety of chronic kidney diseases characterized by glomerulosclerosis and tubulointerstitial fibrosis. "PARP1 is involved in renal fibrosis by binding to the cellular communication network factor 2 promoter in mouse proximal tubule epithelial cells (formerly known as a connective tissue growth factor)." (PMID 35806303, 2022). "The main findings of this work are that inhibition of PARP1 with 5-AIQ ameliorates renal dysfunction and prevents body weight loss, decreasing renal fibrosis and tubular lesions in CisPt treated rats 2 weeks after the treatment." (PMID 29599129, 2018). "Chemical inhibition of PARP1 activity reduces renal fibrosis." (PMID 35806303, 2022). "In consonance with our results, Kim and Padanilam found that PARP1 deficiency in a model of Parp1-KO mice attenuated renal fibrosis and inflammation during unilateral ureteral obstruction but TGF-β1/Smad3 signaling pathway remained unchanged in Parp1-KO and WT mice." (PMID 29599129, 2018). "Parthanatos, a type of programmed cell death, has been found in previous studies to be alleviated by the lack of its key initiator, PARP1, which can reduce renal fibrosis and mitigate renal dysfunction." (PMID 40619276, 2025). "In our work, expression of TGF-β1 was also similar in CisPt and CisPt + 5-AIQ groups and this could explain that inhibition of PARP1 did not achieve a complete protection over renal fibrosis and tubular alterations in CisPt nephrotoxicity." (PMID 29599129, 2018).
serous carcinoma (4 papers, 2020 to 2022). "In addition, another study showed that high expression of PARP1 evaluated by immunohistochemically in 174 sporadic high-grade serous carcinoma patients is associated with a poor outcome when combined with either high or low BRCA expression." (PMID 35875162, 2022). "Additionally, we noticed that the protective effect of PARP1 rs8679 A>G polymorphism was more pronounced among the groups of BMI < 24, menarche age ≤ 14 and serous carcinoma." (PMID 33391423, 2021).
synucleinopathies (4 papers, 2022 to 2024). "Direct and indirect inhibitors of aSyn aggregation, such as KYP-2047, MCC950, and MT101-5, have also shown beneficial effects in rodent models of synucleinopathy, as have poly (ADP-ribose) polymerase-1 (PARP-1) inhibitors like ABT-888 and Veliparib." (PMID 38732162, 2024). "Other approaches focus on targeting various genes or proteins associated with alpha-synucleinopathies, such as glucocerebrosidase, LRRK2, and poly(ADP-ribose) polymerase-1 (PARP-1), or directly target α-syn aggregation using small molecules like Anle138b." (PMID 39666171, 2024).